F2RL3 (F2R like thrombin or trypsin receptor 3)
Description:
Receptor for activated thrombin or trypsin coupled to G proteins that stimulate phosphoinositide hydrolysis. May play a role in platelets activation.
Synonyms: PAR4
Tractability: Small molecule: a drug acting on it is in phase 2 or 3 trials; a high-quality ligand is known; it belongs to a druggable protein family. Antibody: its Gene Ontology location is reachable by antibodies, with high confidence; UniProt places it where antibodies can reach, with medium confidence; UniProt predicts a signal peptide or a membrane-spanning region; the Human Protein Atlas places it where antibodies can reach. PROTAC: ubiquitination databases record sites on it; a small molecule that binds it is known.
Target class: Protease-activated receptor; Membrane receptor; Peptide receptor (family A GPCR); Family A G protein-coupled receptor
Chemical probes: ML354
Gene: Protein-coding gene on chromosome 19 (16,888,999 to 16,892,606, forward strand). Ensembl gene ENSG00000127533.
Subcellular location: Cell membrane
Subcellular location (Human Protein Atlas): Plasma membrane
Pathways (Reactome):
Signal Transduction: G alpha (q) signalling events; Peptide ligand-binding receptors
Hemostasis: Thrombin signalling through proteinase activated receptors (PARs)
Gene Ontology:
Molecular function: protease binding; G protein-coupled receptor activity; thrombin-activated receptor activity
Biological process: platelet activation; positive regulation of release of sequestered calcium ion into cytosol; blood coagulation; G protein-coupled receptor signaling pathway; phospholipase C-activating G protein-coupled receptor signaling pathway; platelet dense granule organization; response to wounding; signal transduction; thrombin-activated receptor signaling pathway
Cellular component: plasma membrane; extracellular region; membrane
Genetic constraint (gnomAD): Loss-of-function variants: 3 observed, 3.8 expected, observed/expected ratio (o/e) 0.79, 90% interval 0.35 to 1.75. That is too few expected variants to judge how well the gene tolerates losing a copy. Missense variants: 564 observed, 475.17 expected, observed/expected ratio (o/e) 1.19, 90% interval 1.11 to 1.27. Synonymous variants: 284 observed, 234.29 expected, observed/expected ratio (o/e) 1.21, 90% interval 1.1 to 1.34.
Homologues: Orthologues: chimpanzee F2RL3 (99% identical), macaque F2RL3 (95% identical), pig F2RL3 (78% identical), mouse F2rl3 (77% identical), rat F2rl3 (75% identical), dog F2RL3 (73% identical), guinea pig F2RL3 (70% identical), tropical clawed frog f2rl3 (39% identical), zebrafish F2RL3 (35% identical). Paralogues in human: F2RL1 (30% identical), F2RL2 (29% identical), F2R (28% identical), P2RY8 (25% identical), GPR4 (22% identical), GPR17 (22% identical), GPR65 (21% identical), LPAR4 (21% identical), P2RY10 (21% identical), CYSLTR2 (21% identical), GPR20 (21% identical), LPAR6 (21% identical), and 4 more.
Diseases named in the same sentence as F2RL3 in open-access papers:
F2RL3 is named in the same sentence as 40 diseases in open-access papers, as found by Europe PMC text mining. Sharing a sentence is not in itself a finding about the gene and the disease. The quoted sentences say what the papers report.
lung carcinoma (10 papers, 2015 to 2024). "Further, F2RL3 methylation was suggested as a biomarker of smoking, and over‐expression and hypo‐methylation were associated with higher risk of lung cancer, and with tumor aggressiveness and poor survival in renal cancer." (PMID 36617746, 2023). "Here, we present data from four prospective cohort studies that convincingly demonstrate that hypomethylation in specific CpG sites of the AHRR and F2RL3 genes is associated with increased risk of subsequent lung cancer." (PMID 26667048, 2015). "We report for the first time that fluorene exposure is associated with the DNA hypomethylation of F2RL3 and AHRR, prospective markers for lung cancer, in the chimney sweeps." (PMID 32385190, 2020). "Specific CpG sites identified here have been found to be associated with lung cancer (cg05951221 and cg21566642 of 2q37.1, cg05575921 of AHRR, cg03636183 of F2RL3), atherosclerosis (cg05575921 of AHRR), body mass index (cg23576855 of AHRR, cg09554443 of CD247), and mortality (cg05575921 of AHRR)." (PMID 29047347, 2017). "To bring some clarity to this question, we used mediation analysis to quantify the amount by which cg05575921 (AHRR gene) and cg03636183 (F2RL3 gene) methylation might mediate the effect of smoking on lung cancer incidence." (PMID 26667048, 2015). "Studies on epigenetic markers—particularly DNA methylation of pivotal genes such as F2RL3 and AHRR, as well as alterations in miRNA profiles affecting gene expression—have emerged as significant indicators for diagnosing and treating lung cancer." (PMID 39440184, 2024). "DNA hypomethylation in factor II receptor-like 3 (F2RL3) and aryl hydrocarbon receptor repressor (AHRR) gene is smoking-related biomarker in blood, which closely correlated with lung cancer incidence and mortality." (PMID 37391844, 2023). "This could partly explain why the methylation pattern of F2RL3 was found to be related to risks for cardiovascular diseases (CVD) and lung cancer, as well as to total mortality." (PMID 26478754, 2015).
coronary artery disease (4 papers, 2012 to 2022). "F2RL3 plays a role in blood coagulation and inflammation, and methylation at cg0363183 has been previously found to be associated with smoking, cardiometabolic traits, coronary artery disease, and morality." (PMID 35039093, 2022). "Lastly, the F2RL3 gene is hypomethylated in smokers and may mediate the detrimental impact of smoking on cardiovascular mortality, since hypomethylated F2RL3 was found to be strongly associated with cardiovascular mortality among patients with stable coronary heart disease." (PMID 22740325, 2012).
thrombotic disease (2 papers, 2013 to 2022). The formation of a blood clot in the lumen of a vessel or heart chamber; causes include coagulation disorders and vascular endothelial injury. "Building on this, we considered whether altered platelet function could serve as a mechanism by which F2RL3 hypomethylation is related to thrombotic disease." (PMID 35012325, 2022).
adrenocortical carcinoma (1 paper, 2022). "Finally, we predicted and verified 8 GRSDMs in adrenocortical carcinoma (ACC), rectum adenocarcinoma (READ), uveal Melanoma (UVM), thyroid carcinoma (THCA), and predicted 4 GRSDMs (F2RL3, DGKB, GRK5, PIK3R6) which were sensitive to 12 potential drugs." (PMID 35885996, 2022).
Alzheimer disease (1 paper, 2015). A progressive, neurodegenerative disease characterized by loss of function and death of nerve cells in several areas of the brain leading to loss of cognitive function such as memory and language. "In this work, we focused on knowledge cliffs next to some of the most-established interactions such as BACE1-APP and found four “potential new candidates”, namely TP53INP2, RTN4, F2RL3, and FBXO2, presumably new targets for Alzheimer’s disease as guided by the knowledge cliff concept." (PMID 26346705, 2015).
colon adenocarcinoma (1 paper, 2025). "Analysis of large cancer datasets reveals that F2RL1 expression is among the highest in colon adenocarcinoma compared to numerous other cancer types, and significantly higher than other PAR family members (F2R/PAR1, F2RL2/PAR3, F2RL3/PAR4) within CRC tissues." (PMID 41002416, 2025).
colon cancer (1 paper, 2018). "The expression of F2RL3 is downregulated in the colon of patients with irritable bowel syndrome patients, while, it is significantly upregulated in patients with colon cancer and ulcerative colitis." (PMID 30186855, 2018).
E. coli infection (1 paper, 2013). "This is in contrast to the many genes identified differentiating the murine response to S. aureus and E. coli infection although F2RL3 is notably absent from this list." (PMID 23326304, 2013).
heart failure (1 paper, 2022). Inability of the heart to pump blood at an adequate rate to meet tissue metabolic requirements. "Here, we specified the significant hypomethylation of F2RL3 in the blood leukocyte DNA of MI and heart failure CHD cases compared to controls and suggested its potential clinical application as a biomarker for the prediction of MI and heart failure." (PMID 35419024, 2022).
inflammatory bowel disease (1 paper, 2025). A spectrum of small and large bowel inflammatory diseases of unknown etiology. "ITGA2B, F2RL3, PTGS1, and ADCY5 were associated with the platelet activation pathway, while IL18 was linked to inflammatory bowel disease (IBD) and the cytokine–cytokine receptor interaction pathways." (PMID 41157169, 2025).
leukemia (1 paper, 2025). A malignant (clonal) hematologic disorder, involving hematopoietic stem cells and characterized by the presence of primitive or atypical myeloid or lymphoid cells in the bone marrow and the blood. "For example, F2RL3 and IL2RA are both involved in inflammation and immune regulation, suggesting they may work together to shape the leukemia microenvironment, potentially contributing to immune suppression and tumor progression." (PMID 40506993, 2025).
myocardial infarction (1 paper, 2022). Gross necrosis of the myocardium, as a result of interruption of the blood supply to the area, as in coronary thrombosis. "We estimated association of the extent of F2RL3 DNA methylation at CpG sites CpG_1 to CpG_4, with risk of incident myocardial infarction in a stratified analysis within smoking status groups (current, former, and never smokers)." (PMID 35012325, 2022). "A HR of 1.31 (95% CI, 1.10–1.56, P=0.003) per SD decrease in F2RL3 DNA methylation at CpG_1 in current smokers (from the fully adjusted model) suggests that observationally, F2RL3 DNA methylation is associated with outcome following a myocardial infarction in this subgroup." (PMID 35012325, 2022).
small intestinal disease (1 paper, 2021). "In our experiment, NSAID-induced small intestinal disease model rats intervened by berberine showed significantly change in HTR4, F2RL3, NPY, CRHR2, IL1b, VIP, AQP8, NOS1." (PMID 34284820, 2021).
cancer (10 papers, 2007 to 2025). A tumor composed of atypical neoplastic, often pleomorphic cells that invade other tissues. "The involvement of PAR4 (also known as F2RL3) in cancer is poorly understood, yet it has emerged as a potent stem cell marker among GPCRs for cancer cell sphere formation, as shown in high-throughput RNA sequencing." (PMID 30400241, 2018). "For example, gene DGKB of UVM in TCGA is specifically high, and gene DGKB was also specifically high in the GEO data set or the testing dataset; DNA methylation levels of gene F2RL3 was significant higher in ACC than other cancer types in the training, testing and GEO validation sets." (PMID 35885996, 2022). "In combined treatment with cisplatin, siRNAs against five genes (ADRA2A, F2RL3, NPSR1, NPY and TACR3) enhanced the anti-proliferation efficacy on cancer cells and reduced the self-recovery ability of surviving cells after the removal of the combined treatment." (PMID 36253428, 2022). "In order to verify reliable GRSDMs, 22 specific DNA methylation genes related to prognosis obtained in the training set were verified on 11 sets of GEO data, and 8 of the specific DNA methylation genes (DGRK, F2RL3, GRK5, NECAB2, OR1C1, OR2L13, OR6F1, and PIK3R6) had been verified in pan-cancer." (PMID 35885996, 2022).
tumor (6 papers, 2015 to 2025). "The F2RL3 (coagulation factor II receptor-like 3) gene encodes for a protease-activated receptor-4 (PAR-4), which has been suggested to be involved in the pathophysiology of both cardiovascular and neoplastic diseases." (PMID 26043106, 2015).
cardiovascular disease (3 papers, 2015 to 2022). "Combined evidence here not only identifies F2RL3 DNA methylation as a possible contributory pathway from smoking to cardiovascular disease risk but from any feature potentially influencing F2RL3 regulation in a similar manner." (PMID 35012325, 2022).
infection (1 paper, 2025). The state of being infected such as from the introduction of a foreign agent such as serum, vaccine, antigenic substance or organism. "With infection, in platelets, associations changed and expression of F2RL3 and GP6 both positively correlated with TLR6, TLR9, RIG-I, MDA5, LGP2, and CGAS." (PMID 40825056, 2025).
F2RL3 also shares sentences with these, for which no sentence is quoted: influenza (2 papers); atherosclerosis (1); autoimmune disease (1); celiac disease (1); colorectal cancer (1); dengue (1); diabetes (1); gastric cancer (1); hematopoietic cancers (1); intestinal cancer (1); irritable bowel syndrome (1); myocardial ischemia (1); osteoarthritis (1); Prader-Willi syndrome (1); prostate carcinoma (1); rectum adenocarcinoma (1); renal carcinoma (1); schizophrenia (1); staphylococcus aureus infection (1); systemic sclerosis (1); thyroid carcinoma (1); ulcerative colitis (1); uveal melanoma (1).